FGF23 (fibroblast growth factor 23)
Diseases named in the same sentence as FGF23 in open-access papers (continued):
Sharing a sentence is not in itself a finding about the gene and the disease.
hyperphosphatemia (continued). "Because hyperphosphatemia can also increase the secretion of FGF23, it is important to control hyperphosphatemia in CKD patients to alleviate cardiac injury." (PMID 32938919, 2020). "In Galnt3−/− mice, breeding with FGF23 transgenic mice can increase the amount of intact FGF23 and reduce hyperphosphatemia." (PMID 32210002, 2020). "The elevation of FGF-23 in CKD is related with hyperphosphatemia and the perpetuation of the reduction of 1,25-dihydroxyvitamin D, which can aggravate the hyperparathyroidism in a vicious cycle." (PMID 32256576, 2020). "In CKD, secondary hyperparathyroidism leads to elevated FGF-23 serum levels, decreased calcitriol production in the kidney, reduced intestinal calcium absorption, and hyperphosphatemia." (PMID 32635646, 2020). "In CKD–mineral and bone disorder, dysregulated FGF23, klotho, vitamin D, and PTH cause progressive hyperphosphatemia, hypercalcemia, and hyperparathyroidism and contribute to the increased cardiovascular risk in patients with renal failure." (PMID 32635646, 2020). "Serum phosphorus concentrations did not significantly increase over time, and it is possible that the increased FGF‐23 concentrations helped control hyperphosphatemia." (PMID 33128421, 2020). "FGF23 is a phosphaturic hormone produced by osteocytes and osteoblasts in response to hyperphosphatemia, hyperparathyroidism, hypercalcemia, and inflammation." (PMID 32718053, 2020). "Evidence that hyperphosphataemia promotes vascular calcification comes from clinical studies with patients suffering from CKD9,30,31 and from hyperphosphataemic FGF23-deficient mice." (PMID 33247205, 2020). "Enhanced PTH release occurs in response to hypocalcemia, hyperphosphatemia, and low 1,25(OH)2D level, whereas high serum levels of calcium, 1,25(OH)2D, or FGF23 suppress PTH production." (PMID 31637056, 2019). "Since FGF23 has been suggested to contribute to complications of CKD, it appears likely that higher calcium and hyperphosphatemia act synergistically on inducing FGF23." (PMID 31505780, 2019). "Both hyperphosphatemia and elevated FGF23 levels promote the development of hypertension, vascular calcification, and left ventricular hypertrophy by distinct mechanisms." (PMID 31698866, 2019). "The direct induction of VC primarily results from hyperphosphatemia, whereas the inflammation-mediated VC is promoted by elevated FGF23 and phosphate levels." (PMID 31698866, 2019). "Targeting FGF23 alone deteriorates the cardiovascular outcome owing to the detrimental effects of hyperphosphatemia." (PMID 31698866, 2019). "Recent publications provide evidence for new promising therapeutic interventions, such as magnesium supplementation and direct targeting of phosphate and FGF receptors to prevent toxicity of FGF23 and hyperphosphatemia in CKD patients." (PMID 31698866, 2019). "FGF23 production in rats is blunted (even in the face of hyperphosphatemia or hyperparathyroidism) if serum calcium concentrations are below a minimum threshold." (PMID 31615041, 2019). "A central role in pathologic cardiovascular remodeling is attributed to hyperphosphatemia and highly elevated fibroblast growth factor 23 (FGF23) levels." (PMID 31698866, 2019). "Enhanced PTH secretion occurs in response to hypocalcemia, hyperphosphatemia, and/or a decrease in serum 1,25-dihydroxyvitamin D (1,25(OH)2D) level, whereas high serum levels of calcium, calcitriol, or FGF23 suppress PTH secretion." (PMID 31637056, 2019). "Recent experimental studies provide evidence for further promising therapeutic strategies, such as direct targeting of phosphate or FGFRs or magnesium supplementation to prevent toxicity of FGF23 and hyperphosphatemia in CKD patients." (PMID 31698866, 2019). "Fibroblast growth factor-23 (FGF-23), a phosphaturic hormone, is mainly synthesized and secreted by osteoblasts and osteocytes in response to hyperphosphatemia and elevated 1.25-dihydroxyvitamin D (1.25-(OH)2D) concentration." (PMID 29726397, 2018).
hyperphosphatemia (continued). "Because FGF23 increases long before hyperphosphatemia ensues during CKD progression, phosphate binders should be started at stages 2 or 3 when serum FGF23 levels, but not serum phosphate levels, start increasing." (PMID 29951315, 2018). "Both the phosphaturic and the 1,25(OH)2D3-lowering effect of FGF23 protect against hyperphosphatemia: the first effect directly through increased elimination of phosphate, and the second effect indirectly through reduced intestinal phosphate absorption." (PMID 29892265, 2018). "Simultaneous treatment with phosphate binders in order to avoid hyperphosphatemia and FGF23 elevation is therefore mandatory in order to control CKD-MBD." (PMID 29808090, 2018). "The resulting reduction in klotho limits its regulation of FGF23 production and leaves hyperphosphataemia as the principal regulator of FGF23 secretion in CKD." (PMID 30348110, 2018). "By mating αKlothoflox/flox mice with these mice, they found mild hyperphosphatemia, modestly elevated serum FGF23 levels, decreased serum levels of PTH, and the abundant expression of the sodium-phosphate co-transporter NPT2A at the brush border membrane." (PMID 29720668, 2018). "As reported by previous investigations, hyperphosphatemia, elevated blood concentration of fibroblast growth factor 23, reduction in active vitamin D synthesis, and tendency toward hypocalcemia are all potent stimuli for secondary hyperparathyroidism." (PMID 30627535, 2018). "In humans with CKD, progressive decreases in klotho occurs in the course of CKD secondary to renal resistance to FGF-23 that results in decreased uFEP values and severe hyperphosphatemia." (PMID 29240673, 2017). "Elevated FGF23 levels in CKD are considered a compensatory mechanism to counteract hyperphosphatemia." (PMID 29250031, 2017). "Abnormal serum levels of FGF23 lead to systemic pathologies in humans, including renal phosphate wasting diseases and hyperphosphatemia." (PMID 27959908, 2016). "Reductions of FGFR1 expression in the proximal tubule resulted in hyperphosphatemia and resistance to the phosphaturic effects of administered recombinant FGF-23." (PMID 26839958, 2016). "Klotho knockout mice and FGF23 knockout mice display a similar pattern of hyperphosphatemia and extensive vascular calcification." (PMID 27668003, 2016). "In particular, FGF23 plasma concentrations are elevated in cats with CKD and associated azotemia and hyperphosphatemia." (PMID 26870965, 2016). "It has been demonstrated that hypercalcemia and hyperphosphatemia increase plasma FGF23 concentrations in mice and cats." (PMID 26870965, 2016). "Hyperphosphatemia stimulates the posterior liberation of fibroblastic growth factor 23 (FGF23) by osteocytes, which inhibits proteins NaPiIIa and NaPiIIc in the proximal convoluted tubule generating phosphaturia." (PMID 27821896, 2016). "High serum FGF23 levels are primarily associated with LVH, whereas low serum Klotho levels and hyperphosphatemia are associated with endothelial dysfunction, atherosclerosis and fibrosis." (PMID 27189482, 2016). "Overexpression of FGF23 in mice leads to hypophosphatemia, hypomineralization, rickets and decreased 1,25-(OH)2D3, whereas ablation of FGF23 in mice leads to hyperphosphatemia, soft tissue calcification and increased 1,25-(OH)2D3." (PMID 27784318, 2016). "The observed hyperphosphatemia in post-menopausal women presumably leads to increased production of FGF23 by bone and this has been demonstrated both experimentally and clinically." (PMID 27176000, 2016). "Although in the presence of hyperphosphatemia, serum FGF-23 levels decreased in the CKD rat model with hypoparathyroidism (PTX+CKD group) and had low bone turnover." (PMID 26186634, 2015). "In CKD, FGF-23 levels increase more than a 100-fold in response to hyperphosphatemia, and elevated FGF-23 levels are predictive of cardiovascular events." (PMID 26217336, 2015).
hyperphosphatemia (continued). "The mineral metabolic abnormalities include hypercalcaemia, hyperphosphataemia, increased circulating concentrations of 1,25 dihydroxyvitamin D and FGF23 as well as osteopaenia." (PMID 25860694, 2015). "In conclusion, the expression of serum FGF-23 was positively correlated with the levels of Pi in MHD patients exhibiting hyperphosphatemia." (PMID 24669256, 2014). "The level of c-terminal FGF23 will be increased, whereas the level of intact FGF23 will be low or inappropriately normal given the level of hyperphosphatemia." (PMID 25249269, 2014). "Consistent with this, mutations in N-acetylgalactosaminyltransferase (GalNac-T3) that cause impaired O-glycosylation results in tumoral calcinosis and hyperphosphatemia due to reduced half-life of FGF23." (PMID 24839967, 2014). "Ablation of FGF23 in mice is lethal in the early postnatal period due to hyperphosphatemia and excessive 1,25(OH)2D production." (PMID 25089825, 2014). "We lack evidence that end-organ resistance to FGF23 actions on the kidney in Hyp;Fgfr1Dmp1-cKO-null mice, since this would lead to hyperphosphatemia and elevated FGF23 levels, a phenotype different from the one observed in these mice." (PMID 25089825, 2014). "At present, mineral disturbances, including hyperphosphatemia and hypercalcaemia, secondary hyperparathyroidism, high FGF23, and adynamic bone disease, are the best known and studied uremic abnormalities associated with development of vascular calcifications." (PMID 24747427, 2014). "Abnormal serum levels of FGF23 result in systemic pathologies in humans and mice, including renal phosphate wasting diseases and hyperphosphatemia." (PMID 25243481, 2014). "The aim of the present study was to investigate the effects of three blood purification methods on fibroblast growth factor-23 (FGF-23) clearance in patients with hyperphosphatemia undergoing maintenance hemodialysis (MHD)." (PMID 24669256, 2014). "As CKD progresses, the compensation of elevations in PTH and fibroblast growth factor-23 (FGF-23) and decreased levels of 1,25(OH)2D3 becomes inadequate and inappropriate, resulting in hyperphosphatemia, abnormal bone, and extraskeletal calcification." (PMID 24558316, 2014). "In the present study, three different blood purification methods; hemodialysis (HD), hemodiafiltration (HDF), and hemodialysis and hemoperfusion (HD+HP), were adopted to compare the clearance efficacy of FGF-23 in MHD patients exhibiting hyperphosphatemia." (PMID 24669256, 2014). "As CKD progresses, compensation for the elevations of PTH and FGF-23 as well as the decreased levels of 1,25(OH)2D3 becomes inadequate, resulting in hyperphosphatemia, hypocalcemia, abnormal bone disorders, and extra-skeletal calcification." (PMID 24587915, 2014). "In fact hypocalcemia, hyperphosphatemia, or reduction in serum fibroblast growth factor 23 (FGF23) results in increased production of PTH that stimulates hydroxylation of 25(OH)D." (PMID 25161666, 2014). "The preclinical development of FGFR inhibitors has been complicated by hyperphosphatemia-mediated tissue calcification, due to the blockade of FGF23 release from bone and of FGF23 signal in kidney." (PMID 23900974, 2013). "In the course of CKD, PTH and FGF-23 levels become elevated prior to the development of hyperphosphatemia." (PMID 23324569, 2013). "Experimental uremia was associated with severely disturbed mineral homeostasis, with significant hyperparathyroidism, hyperphosphatemia, hypocalcemia and very high levels of FGF23." (PMID 24373521, 2013). "The conversion to active vitamin D (1,25[OH]2D) is highly regulated, promoted by PTH and inhibited by FGF23 and hyperphosphatemia." (PMID 23760058, 2013). "A study done in the 5/6 NX rats also showed that cinacalcet promoted hypocalcemia and marked hyperphosphatemia, but serum FGF23 tended to decrease." (PMID 24303131, 2013).
hyperphosphatemia (continued). "Although numerous studies in man and rodents support that FGF23 is stimulated by dietary phosphate intake and hyperphosphatemia, we observed higher levels of circulating FGF23 during hibernation, despite the presence of hypophosphatemia." (PMID 24039826, 2013). "In early stage of CKD, elevation of FGF23 represents an appropriate physiological response to prevent hyperphosphatemia." (PMID 23967103, 2013). "Hyperphosphatemia inhibits 1α-hydroxylation of vitamin D and stimulates FGF23 and PTH production and parathyroid hyperplasia." (PMID 23760058, 2013). "Hyperphosphatemia, increased PTH and FGF23 have been associated with CVD risk in observational studies." (PMID 23587028, 2013). "Serum FGF-23 increases very early in the course of CKD, long before the development of hyperphosphatemia; thus, a high FGF-23 concentration is the most sensitive and earliest marker of disordered phosphorus metabolism in CKD." (PMID 24180481, 2013). "The median phosphate serum concentration was 0.95 mmol/L (range 0.53 to 1.86) at the time of FGF23 concentration measurement and hyperphosphatemia (serum phosphate concentration above 1.40 mmol/L) was present in only 3 patients." (PMID 23825530, 2013). "For example, pan-FGFR inhibitors PD173074 and PD176067 both induced hyperphosphatemia and changes in other FGF23-related parameters." (PMID 23451204, 2013). "Disruption of Klotho (the obligatory co-receptor of FGF23) results in hyperphosphatemia with ectopic calcifications formed in blood vessels and kidneys." (PMID 22879941, 2012). "Fgf23 null mice display increased renal phosphate reabsorption and increased serum 1,25 (OH)2D3 levels, which results in hyperphosphatemia, hypercalcemia, and vascular calcification." (PMID 22879941, 2012). "Both Klotho knockout (Kl−/−) and Fgf23 knockout (Fgf23−/−) mice exhibit hypercalcemia, hyperphosphatemia with low to undetectable PTH levels, and severe osteomalacia." (PMID 22615584, 2012). "The observed hyperphosphataemia in Klotho and FGF23-mutant mice is due to hypervitaminosis D and increased expression/activity of renal sodium-dependent phosphate cotransporters." (PMID 22121479, 2012). "The phenotypes of Fgf23−/− and Klotho−/− (Kl−/−) mice are very similar and include hypercalcemia, hyperphosphatemia, hypervitaminosis D, suppressed PTH levels, and severe osteomalacia/osteoidosis." (PMID 22615584, 2012). "Hyperphosphatemia with serious inflammatory reaction is a common manifestation of CKD, and has been shown to be significantly associated with FGF-23, one of members of FGF family." (PMID 21525989, 2011). "Few reports have analyzed this relationship in AKI patients, although in ESRD a patient's degree of elevation in FGF-23 is often correlated with severity of hyperphosphatemia." (PMID 21906363, 2011). "The hyperphosphatemia associated with CKD most likely triggers FGF-23 production, which promotes renal phosphate excretion, reflected by the severely elevated FGF-23 levels in CKD subjects." (PMID 21234310, 2010). "Therapy with monoclonal anti-FGF-23 antibodies in CKD stages 2 to 4 probably would result in hyperphosphatemia because of reduced urinary phosphate excretion and enhanced 1,25(OH)2D3-dependent intestinal phosphate absorption." (PMID 20593414, 2010). "Here we describe a new mouse model in which we eliminated NaPi2a from Fgf-23 null mice and show reversal of hyperphosphatemia to hypophosphatemia, suggesting that NaPi2a is the major regulator of phosphate homeostasis." (PMID 18688277, 2008). "We have recently generated fibroblast growth factor-23 null (Fgf-23−/−) mice which are characterized by severe hyperphosphatemia, and increased renal expression of NaPi2a." (PMID 18688277, 2008).
hyperphosphatemia (continued). "To test the hypothesis that increased NaPi2a activity is responsible for the severe hyperphosphatemia in Fgf-23−/− animals, we generated a new mouse model deficient in both the Fgf-23 and the NaPi2a genes (Fgf-23−/−/NaPi2a−/− compound mutants) by interbreeding heterozygous- Fgf-23 and NaPi2a mice." (PMID 18688277, 2008). "Targeted disruption of the Fgf-23 gene in mice (Fgf-23−/−) elicits hyperphosphatemia, and an increase in renal sodium/phosphate co-transporter 2a (NaPi2a) protein abundance." (PMID 18688277, 2008). "Genetically altered mice in which Fgf-23 activity is lost exhibit severe hyperphosphatemia accompanied by increased NaPi2a activity, and they develop abnormal bone mineralization." (PMID 18688277, 2008). "Therefore, restricting intestinal P uptake seems to be the best strategy to prevent hyperphosphatemia, hypocalcemia, high FGF23, hyperparathyroidism, and suppressed calcitriol." (PMID 40565034, 2025). "Osteocytes produce Fibroblast Growth Factor 23 (FGF-23) in response to hyperphosphatemia." (PMID 41373697, 2025). "This means that (i) vitamin D supplement use is required in individuals with insufficient or deficient vitamin D status, (ii) physical activity should be recommended in case of bedrest/immobilization, and (iii) P restriction is needed in patients with hyperphosphatemia and/or high FGF23 levels." (PMID 40565034, 2025). "Hyperphosphatemia might contribute to other skin pathologies than calcifications, as suggested by studies in kl/kl and Fgf23−/− mice, which develop skin atrophy." (PMID 40471241, 2025). "Alterations in mineral metabolism are a hallmark of CKD, which includes increases in systemic phosphate levels, also called hyperphosphatemia, as well as elevations in serum levels of fibroblast growth factor 23 (FGF23), which is a bone-derived phosphaturic hormone." (PMID 39273260, 2024). "The absence of the active form of FGF23 due to an inactivating mutation in the FGF23 or lack of FGF23 effect due to a mutation in the Klotho gene can cause hyperphosphatemia, hyperostosis and/or tumoral calcinosis." (PMID 37991698, 2024). "By inhibiting FGFR1, Erdafitinib reduces FGF23 levels, which diminishes the inhibition of sodium-phosphate co-transporters in renal proximal tubules, thereby increasing renal phosphate reabsorption and resulting in hyperphosphatemia." (PMID 39712492, 2024). "Moreover, hyperphosphatemia seems to be related to the increase in the fibroblast growth factor 23 (FGF23) levels and to the decrease in its co-receptor expression, called Klotho, which are ED-inducing factors." (PMID 38791047, 2024). "However, during 2 weeks of increased phosphorus intake in our study, elevated FGF23 combated hyperphosphatemia by inducing effective excretion of phosphate excess." (PMID 39666728, 2024). "In the context of hyperphosphatemia, high phosphate levels, but not activated FGF23/FGFR4 signaling, seem to cause skeletal muscle atrophy, as shown in Col4a3−/− mice." (PMID 38791164, 2024). "In human medicine, increased FGF-23 concentrations precede hyperphosphatemia in patients with CKD." (PMID 37889764, 2023). "Even in animal studies, X-linked hypophosphatemia model mice, which showed high serum FGF23 levels and hyperphosphatemia without kidney dysfunction, did not manifest LVH." (PMID 38174329, 2023). "Notably, bone alterations in these models occurred against the background of hyperphosphatemia and significant changes in the circulating levels of FGF23, PTH, Dickkopf-1, and sclerostin." (PMID 37108433, 2023). "Therefore, perturbation of the klotho-FGF-23 endocrine axes, which accompanies hyperphosphatemia, appears to be a major reason for the premature aging effects from PMWCNTs observed in this study." (PMID 37112600, 2023).